CRP (C-reactive protein)
Diseases named in the same sentence as CRP in open-access papers (continued):
Sharing a sentence is not in itself a finding about the gene and the disease.
diabetes (continued). "On the other hand, in the Mexican population, few studies have shown a relationship between CRP gene variants with blood levels of the protein in obesity, diabetes, and cardiovascular risk." (PMID 23049543, 2012). "Only better aerobic capacity was associated with lower frequency of high C-reactive protein when adjusted to diabetes and gender in a logistic regression model." (PMID 22566996, 2012). "This allele has also been associated with obesity, type 2 diabetes mellitus, coronary artery disease, serum C reactive protein, and insulin resistance." (PMID 22536381, 2012). "Interleukin-1 beta (IL-1β), interleukin 6 (IL-6), and C-reactive protein (CRP) are three inflammatory markers which have been shown to predict the development of diabetes, although this association is interpreted controversially." (PMID 23251619, 2012). "Both CRP and leptin levels were independently associated with several cardiovascular risk factors, including diabetes, hypercholesterolemia and metabolic syndrome in both men and women (P < 0.05)." (PMID 22533665, 2012). "In these analyses, adjustment for GGT and ALT tended to have the strongest effect in terms of attenuating the risk for the association of ferritin with risk of diabetes, whereas adjustment for hs-CRP tended to have a weaker effect." (PMID 22752055, 2012). "Our study group, diagnosed with ACS, was diverse in terms of established risk factors including dyslipidemia, hypertension, diabetes, and smoking; each of them is capable of explaining the occurrence of high CRP concentrations." (PMID 23125484, 2012). "In patients with AoAC at baseline, univariate analysis reavealed that diabetes mellitus, previous cardiovascular disease, lipid-lowering therapy, hs-CRP levels, and baseline AoACS were significantly associated with AoAC progression." (PMID 23144974, 2012). "A third study of 935 women with type 2 diabetes also indicated SDB to be associated with increased CRP after adjusting for age, BMI, lifestyle, family history of diabetes, glycemic control, and medication use." (PMID 22518315, 2012). "In the EPIC-Norfolk cohort, higher ferritin level was associated with diabetes risk after adjustment for conventional risk factors as well as plasma levels of vitamin C, C-reactive protein, fibrinogen, IL-6, liver function tests, ALT, GGT and adiponectin." (PMID 22752055, 2012). "Our findings are consistent with other studies that have reported a significant association between elevated CRP and prediabetes, diabetes or MetS." (PMID 21989115, 2011). "Before adjustment, hypertension, WC, WHR, hs-CRP, and IgE were significant risk factors for pre-diabetes, while high hypertension, WC, WHR, BMI, HOMA-β index, HOMA-IR index, and hs-CRP levels were significant risk factors for diabetes mellitus." (PMID 22194960, 2011). "The primary findings of this study are that elevated levels of CRP and sICAM-1 are associated with increased odds of prediabetes or diabetes, MetS or both conditions in combination." (PMID 21989115, 2011). "Elevated CRP was associated with nearly 2-fold increased odds of prediabetes or diabetes, a 2-fold increased odds of MetS only, and nearly 5-fold increased odds of MetS plus prediabetes or diabetes after multivariable adjustment." (PMID 21989115, 2011). "CRP would predict diabetes with borderline significance in men, whereas in women risk of diabetes would increase significantly with incremental CRP categories and had greater predictive value than fasting glucose level at baseline." (PMID 21603009, 2011). "For example, in obese Zucker rats, the beneficial effect of exercise training on obesity and diabetes has been linked to anti-inflammatory mechanisms, with improvements in the circulating levels of CRP, adiponectin, IL-6, and TNF-α." (PMID 21599899, 2011). "Other associated factors include diabetes, critical illness and a high C-reactive protein (CRP) level." (PMID 21600009, 2011).
diabetes (continued). "Adjustment for baseline determinants of RANTES levels (i.e., sex, diabetes status, presence of bilateral stenosis, CRP) attenuated the association even further (HR [95% CI] 1.01 [0.99–1.01]; p = 0.87)." (PMID 22162987, 2011). "Infuence of interactions between CRP and different variables on the risk of developing pre-diabetes and diabetes mellitus — ordinal logistic model." (PMID 22194960, 2011). "A score consisting of adiponectin, apolipoprotein B, C-reactive protein and ferritin almost doubled the relative risk of diabetes in the validation cohort (HR per one standard deviation increase 1.88, p = 2.8 e-5)." (PMID 20396381, 2010). "In a recent genome-wide association study, several loci including HNF1A which are involved in protein production related to insulin resistance, beta-cell function, weight gain, diabetes and/or early atherogenesis were associated with plasma CRP." (PMID 20716378, 2010). "Metabolic syndrome, type 2 diabetes mellitus and carotid intima-media thickness were associated with shoulder pain in men, whereas high level of C-reactive protein was associated with shoulder pain in women." (PMID 20646281, 2010). "Our study confirms findings by others that elevated C reactive protein is associated with glucose levels, prediabetes, insulin resistance and type 2 diabetes mellitus." (PMID 20659335, 2010). "By far the most data exist on CRP, which has been associated with future diabetes in multiple studies." (PMID 20396381, 2010). "The available biological data have strongly suggested that T2D is an inflammatory disease.Various markers of inflammation predict the future diabetes risk, including IL-6, CRP, sialic acid, and orosomucoid." (PMID 20976133, 2010). "In conclusion, after accounting for classic risk factors, our study identified adiponectin, apoB, CRP, IL-1ra and ferritin as the strongest predictors of incident diabetes." (PMID 20396381, 2010). "In diabetes-free individuals, plasma CRP levels were lower among the S319 allele carriers compared to non-carriers, although both group mean CRP levels were within the average risk range for cardiovascular events (1.0-3.0 mg/L)." (PMID 20716378, 2010). "Risk factors for PAD in patients with diabetes include increasing age, smoking, hypertension, dyslipidemia, neuropathy, and elevated CRP." (PMID 20701768, 2010). "They tested a panel of 58 biomarkers in 160 cases and 472 controls and found that six biomarkers (adiponectin, CRP, ferritin, interleukin-2 receptor A, glucose and insulin) helped to predict the 5-year risk of incident diabetes." (PMID 20396381, 2010). "This, together with the fact that the association was robust to adjustment for CRP, suggests a role for iron overload in the pathogenesis of diabetes." (PMID 20396381, 2010). "In a genome-wide association study, several loci including HNF1A which are involved in protein production related to insulin resistance, beta-cell function, weight gain, diabetes and/or early atherogenesis were associated with plasma CRP." (PMID 20716378, 2010). "A significant difference moderated by diabetes status was found in males associated with both WC (P = 0.004) and BMI (P = 0.009) with ln hs-CRP." (PMID 20617007, 2010). "Elevated C reactive protein (CRP) levels are reported to reflect not only the inflammatory status in type 2 DM but also are associated with other indicators of diabetes-related cardiovascular risk." (PMID 20663222, 2010). "In Laaksonen's study, they examined the association between CRP levels and the development of the metabolic syndrome and diabetes in 680 men with 11 years of follow-up." (PMID 20663138, 2010). "Obesity, a major risk factor for diabetes, is a state of chronic inflammation and is associated with elevated levels of CRP, IL-6 and plasminogen activator inhibitor-1 (PAI-1)." (PMID 20976133, 2010). "Obesity, smoking, diabetes mellitus, metabolic syndrome and high C-reactive protein are all risk factors of atherosclerosis." (PMID 20646281, 2010).
diabetes (continued). "An elevated concentration of C-reactive protein is widely thought to be an indicator of a proinfammatory state and to be associated with higher risk for both cardiovascular disease and diabetes." (PMID 20671994, 2010). "Age, family history of diabetes, waist circumference, systolic blood pressure, and biochemical measures, including CRP and triglycerides, were significantly associated with higher HbA1c levels." (PMID 20875098, 2010). "Elevated circulating levels of certain inflammation markers, namely C-reactive protein (CRP) and interleukin (IL)-6, have been associated with subsequent risk of cardiovascular disease diabetes, and cancer." (PMID 21073739, 2010). "If participants with diabetes were excluded, CRP was the only variable independently associated with fibrinogen (adjusted for age and gender)." (PMID 21029470, 2010). "CRP is influenced by modifiable risk factors such as body mass index, exogenous estrogen, diabetes, hypertension, smoking, alcohol use, HMG-CoA (3-hydroxy-3-methylglutaryl-coenzyme A) reductase inhibitors, aspirin use, physical activity, LDL, and HDL." (PMID 19672401, 2009). "Many known risk factors of diabetes such as C-reactive protein, serum amyloid A and haptoglobin were over-represented in diabetic serum, in agreement with the observations by traditional approaches based on the analysis of individual proteins." (PMID 18795103, 2008). "For example, an interquartileincrease in the 5-day mean PM2.5 (6.1 μg/m3) was associated with a 14% increase in CRP (95% CI, −5.4 to 37%) for all individuals and an 81% (95% CI, 21 to 172%) increase for persons with diabetes, obesity, andhypertension." (PMID 16835049, 2006). "PM2.5 and CRP also exhibited positive associations among all individuals foraverages longer than 1 day, with the largest associations for personswith diabetes, obesity, and hypertension." (PMID 16835049, 2006). "Thus, the role of multiple risk factors, including obesity, smoking, and diabetes, in postoperative spinal infection risk and the reliability of CRP and wound discharge as key infection indicators is reported." (PMID 41960530, 2026). "Elevated inflammatory markers, including white blood cell count, C-reactive protein, and the neutrophil-to-lymphocyte ratio, are frequently observed in patients with type 2 diabetes mellitus and are associated with poor glycemic control and endothelial dysfunction." (PMID 41211065, 2025). "First, biomarkers such as adiponectin, CRP, and IL-6 could be integrated into screening protocols to better identify individuals at risk of lean diabetes." (PMID 41523554, 2025). "However, the mild elevation in CRP, which is seen in abdominal obesity and various chronic conditions such as type 2 diabetes mellitus and cardiovascular disease, was associated with a lower vitamin C status." (PMID 41072799, 2025). "Incorporating clinical risk factors - such as age, parity, family history of diabetes, and body mass index - with biochemical parameters like CRP, uric acid, and PPBS could significantly improve early prediction." (PMID 41200603, 2025). "While there were trends that current smoking, high or low BMI, heavy alcohol drinking, high C-reactive protein levels (> 3mg/L), diabetes mellitus and increase in serum triglycerides are associated with an increased risk of developing wet AMD, none of these associations were significant." (PMID 39930367, 2025). "Moreover, the association between circulating CRP and risk of diabetes and long sleep duration diminished to be statistically non-significant." (PMID 40437222, 2025). "Moreover, high CRP levels have been linked to various diseases like cancer, diabetes, metabolic syndrome, chronic kidney disease, and coronary heart disease." (PMID 40362763, 2025).
diabetes (continued). "Higher BMI (β=0.087, p<0.001), current smoking (β=0.300, p<0.001), diabetes diagnosis (β=0.173, p<0.01), and elevated HbA1c (β=0.114, p<0.001) were all significantly associated with higher CRP levels, underscoring their role as key drivers of systemic inflammation." (PMID 41001317, 2025). "We observed that the groups with hypertension associated with diabetes (G3) and with metabolic syndrome (G4) showed significantly elevated levels of D-dimer, fibrinogen, and C-reactive protein, as well as pronounced leukocytosis with neutrophilia and lymphopenia, when compared with the other groups." (PMID 40862415, 2025). "In general, diabetes and high levels of hs‐CRP are risk factors for ISR in AMI patients after PCI." (PMID 40056066, 2025). "The lower hazard ratio (HR) associated with vitamin D deficiency for incident diabetes at higher CRP levels may indicate a role of inflammation in modifying the effect of vitamin D deficiency." (PMID 39662157, 2025). "By adjusting for covariates (age, sex, energy intake, living area, education level, income, smoking status, physical activity, BMI, hypertension, diabetes, use of dietary supplements, and Hs-CRP level), the linear associations between micronutrient intakes and Hb were explored with RCS." (PMID 41383345, 2025). "The link between inflammation, atherosclerosis, and diabetes suggests that managing inflammation and monitoring CRP could be useful in prognosing the risk of cardiovascular complications in diabetic patients." (PMID 40725102, 2025). "The HP-positive group exhibited a higher prevalence of underlying diseases (e.g., hypertension, diabetes, coronary heart disease) and significant abnormalities in glucose and lipid metabolism, uric acid, high-sensitivity C-reactive protein (hs-CRP), and other indicators." (PMID 40463506, 2025). "One explanation of this result may be that MCR and CRP serum levels are both associated with the same chronic age-related morbidities, such as cardiovascular diseases, diabetes, obesity, and arthritis." (PMID 39913250, 2025). "Therefore, this study aimed to investigate the association between hs-CRP levels and the presence of periodontitis, diabetes mellitus, and their co-existence." (PMID 41153725, 2025). "Similarly, SH2B3, CD40, and CRP are linked to Sjögren’s syndrome, diabetes mellitus, and celiac disease, reinforcing the genetic connections between RA and other autoimmune diseases." (PMID 40839671, 2025). "Secondly, vitamin D and CRP levels may change over time, which may impact the effect of their interaction on diabetes risk." (PMID 39662157, 2025). "The association between CRP/Alb and diabetes in our cohort may reflect regional inflammatory or nutritional patterns, consistent with prior studies." (PMID 41302334, 2025). "This makes CRP a practical and cost-effective tool for integration into cardiovascular risk monitoring protocols, particularly in the context of chronic inflammatory comorbidities like diabetes." (PMID 40725102, 2025). "Both CRP and TyG indices are strongly associated with diabetes." (PMID 40988175, 2025). "Multivariate logistic regression analysis of perioperative mortality revealed that age, sex, BMI, ADL, ASA‐PS classification, alcohol consumption, diabetes mellitus, chemotherapy, radiotherapy, cN, albumin, CRP, and position at the time of MIE were significant risk factors." (PMID 40922930, 2025). "Moreover, numerous factors are known to influence CRP levels, including body mass index, weight loss, smoking, alcohol consumption, and diabetes." (PMID 40114845, 2025). "After adjusting for baseline age, sex, residence (rural/urban), education, smoking, alcohol use, and comorbidity status (hypertension, diabetes, heart disease), undernutrition exposure was linked to higher odds of abnormal CRP (adjusted OR = 1.46, 95% CI: 1.22–1.75, p < 0.001)." (PMID 40936900, 2025).
diabetes (continued). "In a study by Xia Li, it was found that IL-6, IL-8, hypercholesterolemia, diabetes mellitus, and high-sensitivity C-reactive protein (hs-CRP) were independent predictors of restenosis risk in CAD patients who underwent percutaneous coronary intervention with drug-eluting stents." (PMID 39859253, 2025). "Hypersensitive C-reactive protein-atherogenic index (CAI) may serve as a novel marker for metabolic dysfunction-associated steatotic liver disease (MASLD) in type 2 diabetes mellitus (T2DM)." (PMID 41347130, 2025). "Blood-CRP level is associated with sleep duration and diabetes." (PMID 40437222, 2025). "Additionally, HS was inversely associated with CRP, even after adjusting for classical diabetes risk factors." (PMID 41276872, 2025). "Similarly, in Saudi Arabia, ICU admission was linked to age, diabetes, heart failure, CRP, and respiratory distress, while mortality was strongly predicted by oxygen desaturation, thrombocytopenia, and elevated troponin." (PMID 41020217, 2025). "Mortality has been observed in 19% of cases, and the presence of diabetes mellitus, substantial cerebral edema and hemorrhage on imaging, a delay in the resolution of the etiology, increased C-reactive protein, and involvement of the corpus callosum are associated with negative outcomes in PRES." (PMID 39712751, 2024). "However, the association between CRP and cardiovascular mortality in diabetes patients is controversial." (PMID 38570824, 2024). "This study hypothesized that LDL cholesterol, insulin resistance, and C-reactive protein mediated the association between triglycerides and diabetes." (PMID 38611646, 2024). "In line with established risks factors, the risk of evolution towards severe pneumonia was associated with age, diabetes, temperature, C-reactive protein (CRP), procalcitonin, fibrinogen, neutrophils and lymphocytes at inclusion, oxygen saturation and CT scan findings." (PMID 38772950, 2024). "TMPRSS2 and aromatase were both increased in non-survivors and independently associated (p < 0.01) with mortality after adjusting for several baseline risk variables (including age, sex, CRP, hypertension, hyperlipidemia, and diabetes) in a multivariate logistic regression model." (PMID 39449074, 2024). "When assessing the associations between SSc disease-specific, demographic, and cardiovascular parameters with CRP positivity, we found that suffering from type 2 diabetes mellitus increased the risk of having a prolonged CRP−positive status by 5.3-fold (OR: 5.25 [0.87–31.52] p = 0.070)." (PMID 39564499, 2024). "Clinical variables such as hypertension, diabetes, heart failure, and laboratory findings such as abnormal levels of troponin I, N-terminal proBNP, and C-reactive protein are associated with increased hospitalization complications and mortality due to CoV-19 infection." (PMID 39011427, 2024). "Includes therapy, dental implants, alveolar bone loss, diagnosis, radiography, apical periodontitis, surgery, management Group 4 contains 26 keywords (in yellow) and includes risk, diabetes, metabolic syndrome, blood pressure, insulin-resistance, c-reactive protein, markers, glycemic control." (PMID 38800469, 2024). "Finally, the Cardiovascular Health Study in the United States showed that having baseline CRP in the highest quartile was associated with increased odds of developing diabetes (OR 2.03 [1.44 - 2.86]) versus the lowest quartile." (PMID 38665261, 2024). "In RA patients, CRP is a reliable marker of systemic inflammation, and its levels appear to be related with the risk of associated comorbidities, like cardiovascular diseases, diabetes, metabolic syndrome, pulmonary diseases, and depression." (PMID 38886765, 2024).